HADHB (hydroxyacyl-CoA dehydrogenase trifunctional multienzyme complex subunit beta)
Description:
Mitochondrial trifunctional enzyme catalyzes the last three of the four reactions of the mitochondrial beta-oxidation pathway. The mitochondrial beta-oxidation pathway is the major energy-producing process in tissues and is performed through cycles of four consecutive reactions. Each beta-oxidation cycle shortens the fatty acyl-CoA by two carbons, yielding one acetyl-CoA (for the citric acid cycle), one FADH(2), and one NADH (which donate electrons to the respiratory chain for ATP production). These cycles repeat until the chain is fully degraded to acetyl-CoA units. Among the enzymes involved in this pathway, the trifunctional protein, responsible for the hydration, dehydrogenation, and thiolysis steps, shows specificity for long-chain fatty acids, such as those from dietary and stored fats. Mitochondrial trifunctional enzyme is a heterotetrameric complex composed of two proteins, the trifunctional enzyme subunit alpha/HADHA carries the 2,3-enoyl-CoA hydratase and the 3-hydroxyacyl-CoA dehydrogenase activities while the trifunctional enzyme subunit beta/HADHB described here bears the 3-ketoacyl-CoA thiolase activity. These activities have been experimentally confirmed on a few substrates derived from beta-oxidation of long-chain saturated fatty acids such as palmitate (hexadecanoate) and laurate (dodecanoate). In addition, based on its established catalytic mechanism, and combined genetic interaction or mutant phenotype evidence, it is predicted to act also on other substrates, including long-chain unsaturated fatty acids such as oleate (9Z-octadecenoate), linoleate (9Z,12Z-octadecadienoate), linolenate (9Z,12Z,15Z-octadecatrienoate), and others (Probable).
Synonyms: MSTP029; MTPB; ECHB; MTPD; MTPD2; TP-BETA
Tractability: PROTAC: ubiquitination databases record sites on it; its protein half-life has been measured.
Target class: Enzyme; Transferase
Gene: Protein-coding gene on chromosome 2 (26,243,170 to 26,290,467, forward strand). Ensembl gene ENSG00000138029.
Subcellular location: Mitochondrion; Mitochondrion inner membrane; Mitochondrion outer membrane; Endoplasmic reticulum
Subcellular location (Human Protein Atlas): Mitochondria; Equatorial segment; Principal piece
Pathways (Reactome):
Metabolism: Acyl chain remodeling of CL; Beta oxidation of decanoyl-CoA to octanoyl-CoA-CoA; Beta oxidation of hexanoyl-CoA to butanoyl-CoA; Beta oxidation of lauroyl-CoA to decanoyl-CoA-CoA; Beta oxidation of myristoyl-CoA to lauroyl-CoA; Beta oxidation of octanoyl-CoA to hexanoyl-CoA; Beta oxidation of palmitoyl-CoA to myristoyl-CoA; mitochondrial fatty acid beta-oxidation of unsaturated fatty acids
Gene Ontology:
Molecular function: acetyl-CoA C-acyltransferase activity; acetyl-CoA C-myristoyltransferase activity; protein binding; RNA binding; (3S)-3-hydroxyacyl-CoA dehydrogenase (NAD+) activity; enoyl-CoA hydratase activity; acetyl-CoA C-acetyltransferase activity; acyltransferase activity; acyltransferase activity, transferring groups other than amino-acyl groups; lncRNA binding; protein-containing complex binding
Biological process: fatty acid beta-oxidation; cellular response to lipopolysaccharide; gene expression
Cellular component: endoplasmic reticulum; mitochondrial fatty acid beta-oxidation multienzyme complex; mitochondrial inner membrane; mitochondrial nucleoid; mitochondrial outer membrane; mitochondrion; mitochondrial envelope
Genetic constraint (gnomAD): Loss-of-function variants: 15 observed, 20.17 expected, observed/expected ratio (o/e) 0.74, 90% interval 0.5 to 1.14. The upper end of that interval is the gene's LOEUF score, 1.14, which puts it in group 5 of 6, group 1 being the genes least tolerant of losing a copy. Missense variants: 254 observed, 292.99 expected, observed/expected ratio (o/e) 0.87, 90% interval 0.78 to 0.96. Synonymous variants: 99 observed, 108.68 expected, observed/expected ratio (o/e) 0.91, 90% interval 0.77 to 1.08.
Gene-disease validity (ClinGen):
ClinGen rates the evidence that HADHB causes each of these diseases.
mitochondrial trifunctional protein deficiency (autosomal recessive): Definitive.
Homologues: Orthologues: chimpanzee HADHB (99% identical), dog HADHB (92% identical), pig HADHB (91% identical), guinea pig HADHB (91% identical), mouse Hadhb (91% identical), rat Hadhb (90% identical), tropical clawed frog hadhb (82% identical), zebrafish hadhb (76% identical), Drosophila melanogaster Mtpbeta (65% identical), Caenorhabditis elegans hadb-1 (57% identical). Paralogues in human: ACAA1 (31% identical), ACAA2 (29% identical), ACAT1 (29% identical), ACAT2 (28% identical).